SERPINC1 (serpin family C member 1)
Diseases named in the same sentence as SERPINC1 in open-access papers (continued):
Sharing a sentence is not in itself a finding about the gene and the disease.
myopathy (1 paper, 2015). A disease of the muscle in which the muscle fibers do not function properly. "Birds suffering from this myopathy exhibit down-regulation of eight hemostatic genes (A2M, FGA, FGB, FGG, KNG1, SERPINC1 and VWF) and up-regulation of four other coagulation genes (F5, F10, PROS1 and F2R)." (PMID 26445145, 2015).
SERPINC1 also shares sentences with these, for which no sentence is quoted: coagulopathy (33 papers); hyperhomocysteinemia (25); antiphospholipid syndrome (21); liver disease (17); Thrombocytopenia (16); Cirrhosis (12); liver cirrhosis (10); atherosclerosis (9); liver dysfunction (9); Hypoalbuminemia (7); pancreatic cancer (7); Portal vein thrombosis (7); protein c deficiency (7); central nervous system lymphoma (6); Thrombocytosis (6); myocardial infarction (5); preeclampsia (5); viral infection (5); acute kidney injury (4); AL amyloidosis (4); breast carcinoma (4); cardiomyopathy (4); dysfibrinogenemia (4); hereditary thrombophilia (4); leukemia (4); liver failure (4); pancreatitis (4); portal hypertension (4); protein S deficiency (4); Protein-losing enteropathy (4).
A further 205 diseases each share a sentence with SERPINC1 in 4 papers or fewer.